CENPS-CORT (CENPS-CORT readthrough)
Synonyms: APITD1-CORT
Gene: Protein-coding gene on chromosome 1 (10,430,102 to 10,452,153, forward strand). Ensembl gene ENSG00000251503.
Genetic constraint (gnomAD): Loss-of-function variants: 17 observed, 16.55 expected, observed/expected ratio (o/e) 1.03, 90% interval 0.7 to 1.54. The upper end of that interval is the gene's LOEUF score, 1.54, which puts it in group 6 of 6, group 1 being the genes least tolerant of losing a copy. Missense variants: 160 observed, 159.1 expected, observed/expected ratio (o/e) 1.01, 90% interval 0.88 to 1.15. Synonymous variants: 49 observed, 54.72 expected, observed/expected ratio (o/e) 0.9, 90% interval 0.71 to 1.14.